MACC1 (MET transcriptional regulator MACC1)
Diseases named in the same sentence as MACC1 in open-access papers (continued):
Sharing a sentence is not in itself a finding about the gene and the disease.
colon carcinoma (85 papers, 2011 to 2025). "The metastasis-associated in colon cancer 1 (MACC1) gene was first identified by a genome-wide analysis of genes which are differentially expressed in human colon cancer tissues, metastases and normal tissues." (PMID 38339354, 2024). "Recently, the critical roles of MACC1 (metastasis-associated in colon cancer-1) in cancer progression, invasion and metastasis has been recognized in colon cancer and various other types of cancer." (PMID 37496665, 2023). "As the term suggests, metastasis-associated in colon cancer 1 (MACC1) is generally correlated with the metastasis of colon cancer." (PMID 37519791, 2023). "The proteins associated with MACC1 promoter binding were different in colon cancer cells with different metastatic potentials." (PMID 37020597, 2023). "MACC1 controls gene transcription, promotes motility, invasion and proliferation of colon cancer cells in vitro, and causes tumor growth and metastasis in mice." (PMID 38144523, 2023). "MACC1 (Metastasis Associated in Colon Cancer 1) acts in colon cancer as a metastasis inducer and is linked to reduced survival." (PMID 35406545, 2022). "The gene, metastasis-associated in colon cancer 1 (MACC1), is a biomarker predictive of both metastatic and metastasis-free survival in patients with colon cancer and other solid tumors." (PMID 36545127, 2022). "Our results demonstrate a reciprocal interplay between the circadian clock and the metastasis associated gene MACC1 (metastasis-associated in colon cancer 1), pointing to the circadian clock-regulation of CRC invasiveness." (PMID 35884519, 2022). "As shown in the Venn diagram, the intersection showed two differentially expressed mRNAs: MACC1 (metastasis-associated in colon cancer-1) and LHFPL2 (lipoma HMGIC fusion partner-like 2)." (PMID 35279159, 2022). "SH3BP4 is a gene paralog with approximately 50% shared nucleotide sequences with MACC1 (Metastasis-Associated In Colon Cancer Protein 1), an independent colon cancer prognostic marker." (PMID 36741706, 2022). "Metastasis-associated in colon cancer-1 (MACC1) was first identified in colon cancer and was suggested as an oncogene 13-15." (PMID 32047570, 2020). "Metastasis-associated in colon cancer-1 (MACC-1) is a newly identified tumor marker, first identified in colon cancer tissue as a prognostic indicator and inducer of metastasis." (PMID 33400729, 2020). "Metastasis-associated in colon cancer-1 (MACC-1) is a newly identified tumor marker, found to express in various normal and cancerous tissue." (PMID 33400729, 2020). "Some researchers have focused on mRNA expression of genes related to lymph nodes, such as guanylyl cyclase C (GCC) and metastasis associated in colon cancer 1 (MACC1), to evaluate colon cancer prognosis." (PMID 31182111, 2019). "The clinical significance of metastasis‐associated in colon cancer‐1 (MACC1) has been investigated but the relevance of peripheral MACC1 levels was rather limited." (PMID 30370603, 2019). "The PRD domain in the metastasis-associated in colon cancer protein 1 (MACC1) is required for its oncogenic function in colon cancer growth and metastasis." (PMID 29228664, 2017). "Metastasis-associated in colon cancer-1 (MACC1) is an oncogene first discovered in colon cancer, where its main action was thought to be promotion of metastasis." (PMID 26919111, 2016). "We identified the novel gene Metastasis Associated in Colon Cancer 1, MACC1, based on human colon cancer specimens." (PMID 25884643, 2015). "The overexpression of metastasis-associated in colon cancer 1 (MACC1) has been demonstrated not only in colon cancer, but also in various other types of cancer." (PMID 26043756, 2015). "The metastasis-associated in colon cancer 1 (MACC1) gene was initially identified in a genome-wide search for differentially expressed genes in human colon cancer primary tissue samples, metastatic tissue samples, and normal tissue samples." (PMID 26043756, 2015).
colon carcinoma (continued). "Mechanistically, miR-143 was identified to target metastasis-associated in colon cancer-1 (MACC1), a novel prognostic biomarker for metastasis occurrence, which was overexpressed in colon cancer and other cancer types." (PMID 26064956, 2015). "MACC1 is a strong prognostic biomarker for colon cancer metastasis and allows identification of high-risk subjects in early stages, when determined in patients’ primary tumors." (PMID 23166620, 2012). "High expression levels of MACC1 have been associated with colon cancer metastasis and reduced survival." (PMID 22251819, 2012). "The expression of the newly identified gene metastasis associated in colon cancer 1 (MACC1) is a prognostic indicator for colon cancer metastasis." (PMID 22838389, 2012). "Metastasis-associated in colon cancer-1 (MACC1), a new gene associated with colon cancer in primary and metastatic carcinomas, promotes tumour cell growth as well as the development of distant metastases." (PMID 21955323, 2011). "Metastasis-associated in colon cancer-1 (MACC1) is a newly identified gene that plays a role in colon cancer metastasis through upregulation of c-MET proto-oncogene (c-MET)." (PMID 21955323, 2011). "MACC1 is closely associated with several types of cancer, and can serve as poor prognosis and metastatic biomarker for colon cancer, gastric carcinoma, lung cancer, and hepatocellular carcinoma." (PMID 21923915, 2011). "MACC1 was demonstrated to be associated with poor prognosis and high risk of metastasis in colon cancer, gastric carcinoma, lung cancer, and hepatocellular carcinoma." (PMID 21923915, 2011). "However, one study found a connection between miR-598 and the Metastasis Associated Colon Cancer (MACC1) gene through direct inhibition." (PMID 39801574, 2024). "Metastasis associated in colon cancer 1 (MACC1) is an oncogene first identified in colon cancer." (PMID 36979146, 2023). "Moreover, HCP5 can encourage the development of cervical cancer by inhibiting microRNA-15a regulating metastasis-associated in colon cancer-1 (MACC1)." (PMID 34222007, 2021). "MACC1 has been discovered as metastasis-associated expressed protein in colon cancer." (PMID 31200581, 2019). "Another candidate is MACC1 (metastasis-associated in colon cancer 1) which was identified in 2009 in a genome-wide search for genes that were differentially expressed between samples from healthy, colon cancer and metastatic tissue." (PMID 31671891, 2019). "Metastasis-associated in colon cancer 1 (MACC1) has recently been identified as a novel independent prognostic indicator for metastasis occurrence, overall survival and cancer-free survival for patients with colon cancer and other solid tumors." (PMID 24949951, 2014). "We thus found NPFs in several enhancer-binding proteins, notably in RUNX and Osa/ARID1 (the DNA-binding subunit of SWI/SNF chromatin remodeling complexes; Wu and Roberts, 2013), and also in MACC1 (metastasis-associated in colon cancer 1) whose molecular function is unknown." (PMID 26312500, 2015). "Indeed, MACC1 translocation from the cytoplasm to the nucleus has been indicated to be intimately associated with metastasis in colon cancer cells and may very well indicate the higher malignancy in the case of glioma cells." (PMID 24949951, 2014). "Using online miRNA target prediction databases (miRNA.org and Targetscan), we hypothesized that metastasis-associated in colon cancer-1 (MACC1), which has been newly identified as a positive prognostic indicator of metastasis formation in CRC, was a target of miR-143." (PMID 22533346, 2012). "The gene Metastasis-Associated in Colon Cancer 1 (MACC1), discovered in 2009, exhibits a close association with the occurrence and metastasis of colon cancer." (PMID 40354443, 2025). "In vitro analyses have demonstrated that MACC1-expressing colon cancer cell lines exhibit poor response to irinotecan, 5-fluorouracil (5FU), and cisplatin." (PMID 39580452, 2024).
colon carcinoma (continued). "In contrast to normal colon mucosa, MACC1 displays highly elevated expression levels in primary and metastasized colon cancer tissues." (PMID 38339354, 2024). "used CRISPR-CHAP-MS (Mass spectrometry-based proteomic capture of proteins) to study the binding protein of the MACC1 promoter region of colon cancer." (PMID 37020597, 2023). "MACC1, first identified as novel gene in tissues of colon cancer patients, is a predictor for CRC metastasis and metastasis-free survival." (PMID 38144523, 2023). "MACC1 expression induced metastasis of colon cancer, and the binding of HNF4G and PAX6 to the promoter was verified." (PMID 37020597, 2023). "The involvement of MACC1 in regulating the HGF/c-Met signaling pathway has been confirmed in cancers such as colon cancer, breast cancer, ovarian cancer, lung cancer, liver cancer, gastric cancer, mesocortical tumor, malignant brain tumor, and kidney cancer." (PMID 36979146, 2023). "The results showed that the overexpression of MACC1 accelerated the proliferation, migration, and invasion rate of colon cancer cells (P < 0.01)." (PMID 35874635, 2022). "We tested NCM460, SW480, HCT116, SW620, and HT-29 cell lines that are commonly used in colon cancer research in this experiment, and the results demonstrated that MACC1 in colon cancer cell lines has high expression." (PMID 35874635, 2022). "To this end, we performed gene intervention (overexpression or silencing) with MACC1 in colon cancer cell lines." (PMID 35874635, 2022). "With further exploration, we proved that c-MET is downstream of MACC1 in colon cancer and that overexpression of c-MET in colon cancer enhances cell proliferation and migration capability." (PMID 35874635, 2022). "After 72 h of observation, overexpression of MACC1 led to a significant increase in the proliferation of colon cancer cells." (PMID 35874635, 2022). "Genome-wide analysis of genes differentially expressed in primary colon cancer, metastatic tumors and normal tissues has shown that MACC1 is an independent prognostic indicator of metastasis-free survival." (PMID 36545127, 2022). "In order to further explore the regulatory role of MACC1 in colon cancer, we conducted a series of experiments on colon cancer cell lines related to malignant tumors." (PMID 35874635, 2022). "We studied the role of MACC1 in COAD and extracted the expression levels of MACC1 in colon cancer tissues and normal tissues from the TCGA database (P < 0.01)." (PMID 35874635, 2022). "The MTT assay was used to assess the impact of MACC1 expression on the proliferation of colon cancer cells." (PMID 35874635, 2022). "MACC1 is a known driver for cancer metastasis, especially in colon cancer, as well as other solid tumours, and is considered to be a therapeutic target in CRC restricting metastasis." (PMID 36012399, 2022). "In our study, we found that MACC1 has significantly higher expression in colon cancer tissues than in the surrounding colon tissues." (PMID 35874635, 2022). "To investigate the effect of MACC1 on colon cancer, we extracted the expression pattern of MACC1 in various cancers in the TCGA database." (PMID 35874635, 2022). "There is a positive correlation between the expression of MACC1 and the proliferation and migration of colon cancer cells." (PMID 35874635, 2022). "The result indicated that the expression of MACC1 in colon cancer cell lines was also markedly higher (P < 0.01)." (PMID 35874635, 2022). "Tissue microarrays containing 270 colon cancers in two groups, that is, MACC1high and MACC1low, were used to analyze the prognostic value of MACC1 in colon cancer." (PMID 35874635, 2022). "Studies have shown that the expression of MACC1 is changed in various tumors, especially in colon cancer, gastric cancer, and liver cancer." (PMID 35874635, 2022). "MACC1, an oncogene on human chromosome 7p21.1, is an important premetastasis factor of human colon cancer." (PMID 35874635, 2022).
colon carcinoma (continued). "In order to assess the influence of regulation of MACC1 on the proliferation, migration, and invasion of colon cancer cells, we conducted a cloning experiment, wound healing, and invasion experiment." (PMID 35874635, 2022). "MACC1 was first described in 2009 as a critical pro‐metastatic TF regulating HGF/c‐Met signaling axis in human colon carcinoma." (PMID 33751856, 2021). "MACC1 is a new gene discovered by Stein, who analyzed the differential expression in normal colon mucosa, colon adenoma and colon cancer tissues." (PMID 34343214, 2021). "MACC1 is a vital gene with the invasive behaviors and postoperative liver metastasis in colon cancer." (PMID 32595704, 2020). "Metastasis-associated in colon cancer 1 (MACC1) is a prognostic and predictive biomarker for metastasis formation and metastasis-free survival of patients with colon cancer and other solid tumors." (PMID 31200581, 2019). "Metastasis‐ associated in colon cancer 1 (MACC1), identified in colon cancer patients in 2009 for the first time, has been found to play multiple important roles in tumourigenesis and metastasis." (PMID 30370603, 2019). "For example, metastasis-associated in colon cancer 1 (MACC1), identified in colon cancer patients for the first time, has been found to play multiple important roles in many malignancies, such as hepatocellular cancer and lung cancer." (PMID 31019967, 2019). "Accumulating studies suggest that MACC1 is a prognostic and metastatic biomarker for colon cancer and various other cancers." (PMID 30082743, 2018). "Loss of DBC1 results in deregulation of MACC1 target gene expression, and DBC1 is required for cell proliferation, EMT properties, CSC-like traits, and drug resistance potential of colon cancer cells." (PMID 30082743, 2018). "We next assessed the effects of iCRT14, a β-catenin-TCF complex inhibitor, and β-catenin knockdown on MACC1 expression in colon cancer cells." (PMID 30082743, 2018). "Metastasis-associated in colon cancer 1 (MACC1) gene, a novel regulator of tumor growth and metastasis, has recently been identified in colon cancer." (PMID 30515418, 2018). "Metastasis-associated in colon cancer 1 (MACC1) was overexpressed in many tumors, including colon cancer, human lung cancer, hepatocellular carcinoma and human malignant glioma." (PMID 28348518, 2017). "Metastasis-associated in colon cancer-1 (MACC1) was originally identified as a metastatic and prognostic biomarker for colon cancer and later other solid tumors." (PMID 27793161, 2016). "The MACC1 gene was discovered by a genome-wide search in human colon cancer tissues, metastases, and normal tissues." (PMID 26884752, 2016). "MACC1 was first identified in colon cancer in 2009 and was bound to the promoter of the mesenchymal-epithelial transition (MET) gene to control its transcriptional activity." (PMID 27793161, 2016). "High expression levels of MACC1 correlate positively with colon cancer metastases and reduced metastasis-free survival." (PMID 26884752, 2016). "Previous studies have suggested that MACC1 is expressed not only in colon cancer, but also in various other human cancers, including lung cancer, hepatocellular carcinoma, ovarian carcinoma and gastric carcinoma." (PMID 26043756, 2015). "Further studies have shown that MACC1 is overexpressed not only in colon cancer, but also in other carcinomas, including hepatic and lung cancer." (PMID 25009663, 2014). "A recent study in vitro identified that concomitant downregulation of miR-1 and increase of metastasis-associated in colon cancer 1 (MACC1) can contribute to MET overexpression and to the metastatic behavior of colon cancer cells." (PMID 25196260, 2014). "MACC1, a recently identified metastasis-related gene, was identified by differential display qPCR of the normal colon, primary colon cancer and metastatic tissues." (PMID 25009663, 2014).
colon carcinoma (continued). "It has been reported that down-regulation of miR-1 and increase of MACC1 contributed to overexpression of Met in human colon cancer." (PMID 24936152, 2014). "Here we report the development of the first blood-based assay for the metastasis-inducing gene MACC1, which is a prognostic biomarker for colon cancer metastasis as well as for tumor progression and survival in a variety of solid cancers." (PMID 23166620, 2012). "In this study, high expression levels of MACC1 correlates positively with colon cancer metastasis and reduced metastasis-free survival." (PMID 22251819, 2012). "MACC1 is a new prognostic biomarker for colon cancer metastasis and metastasis-free survival when determined in patients’ primary tumors." (PMID 23166620, 2012). "The previously undescribed gene MACC1 (formerly designated as 7a5) was discovered by a genome-wide search for differently expressed genes in human colon cancer tissues, metastases, and normal tissues." (PMID 22251819, 2012). "Metastasis associated in colon cancer 1 (MACC1) gene was first identified in 2009 as a key regulator of hepatocyte growth factor-mesenchymal-epithelial transition factor (HGF-MET) signaling and the expression of MACC1 in tumor specimens is an independent prognostic factor for colon cancer." (PMID 38021160, 2023). "The gene metastasis-associated in colon cancer 1 (MACC1) was identified over a decade ago from a different display of RT-qPCR examining colon mucosa, primary tumors of stage I-III and stage IV, and metastases of subjects with colon cancer." (PMID 36674695, 2023). "From the result, MACC1 in colon cancer tissues had significantly upregulated expression (P < 0.01)." (PMID 35874635, 2022). "Then, we identified the MACC1/HGF/c-MET axis in colon cancer and tried to explore whether this axis could interfere with colon cancer invasion and metastasis by regulating MACC1 or by blocking the expression of downstream c-MET." (PMID 35874635, 2022). "In addition, the hazard ratio of MACC1 (HR = 2.1, P=0.0031) was also calculated, and the result suggested that MACC1 is a prognostic factor for colon cancer." (PMID 35874635, 2022). "Furthermore, the mRNA expression level of MACC1 in multiple colon cancer cell lines (SW480, HCT116, SW620, and HT-29) and one normal colon epithelium cell line (NCM460) was examined." (PMID 35874635, 2022). "MACC1 expression in colon cancer cell lines was compared with the baseline expression levels." (PMID 35874635, 2022). "Finally, in the mouse model, the effect of MACC1 on colon cancer was consistent with that in the cellular model." (PMID 35874635, 2022). "MACC1 high expression occurred preferentially in colon tumors at the distal sites." (PMID 35406521, 2022). "In the EdU cell proliferation assay, MACC1 overexpressing colon cancer cells had much stronger staining intensity, while MACC1 knockdown colon cancer cells had significantly weaker staining intensity, demonstrating the positive effect of MACC1 on the growth of colon cancer (P < 0.01)." (PMID 35874635, 2022). "The results indicated that the overexpression of MACC1 could accelerate proliferation and facilitate metastasis in colon cancer cell lines." (PMID 35874635, 2022). "Notably, the expression of MACC1 was upregulated in multiple mucosa malignancies, including colon adenocarcinoma (colon cancer), rectal carcinoma (READ), and stomach adenocarcinoma (STAD)." (PMID 35874635, 2022). "Metastasis associated with the colon cancer-1 (MACC1) gene, which plays an important role in regulating the hepatocyte growth factor (HGF)/MET signaling pathway, is recognized as a prognostic biomarker for colon cancer." (PMID 34072650, 2021). "Recently, RT-qPCR and dPCR of MACC1 and S100A4 (metastasis-associated in colon cancer 1 and S100 calcium-binding protein A4, respectively) transcripts in serum have been correlated with diagnosis, progression-free survival and overall survival of ovarian cancer." (PMID 34067294, 2021).